INS (insulin)
Diseases named in the same sentence as INS in open-access papers (continued):
Sharing a sentence is not in itself a finding about the gene and the disease.
diabetes (continued). "However, regular phone contact from a diabetes educator encouraged people to adjust insulin dosage, leading to better glycaemic control." (PMID 28750628, 2017). "In fact, administration of different doses of exocarp extracts to STZ-induced diabetic rats resulted in a significant decline in blood glucose levels, an increased plasma insulin level, as well as decreased levels of fructosamine and glycated haemoglobin, two diabetes status indicators." (PMID 28531110, 2017). "Therefore, we investigated the superiority of dapagliflozin on glucose fluctuation compared with DPP-4 inhibitors in patients with type 2 diabetes mellitus (T2DM) on insulin using a continuous glucose monitoring (CGM) system." (PMID 28725273, 2017). "It is known that the required initial daily insulin dose may vary according to many factors including age, body weight, stage of puberty, duration and phase of diabetes." (PMID 28044993, 2017). "Type 1 diabetes mellitus (T1DM) is an autoimmune disease mainly mediated by effector T cells that are activated by autoantigen, thereby resulting in the destruction of pancreatic islets and deficiency of insulin." (PMID 28947964, 2017). "Furthermore, chronic excessive activation of NADPH oxidase in beta cells is a mediator of the failure of glucose-stimulated insulin secretion and of the beta cell apoptosis that collaborate with systemic insulin resistance to usher in overt diabetes." (PMID 28335416, 2017). "However, despite the lowered insulin levels, Prep1i/+ mice are protected from streptozotocin-induced diabetes and feature reduced lipotoxicity and diet-induced steatohepatitis." (PMID 29069751, 2017). "Additionally, the effect of insulin therapy on the expression of selected GLUT isoforms in the placenta of women with diabetes was analyzed." (PMID 27981520, 2017). "Moreover, several clinical studies have demonstrated a positive correlation between diabetes and AD, and suggested that the central reasons for this include aberrant insulin signaling and dementia." (PMID 28764741, 2017). "The meta-analysis of epidemiological studies concerning the consumption of meat has shown that meat intake is associated with fasting glucose and insulin concentrations in Caucasians without diabetes mellitus." (PMID 29258212, 2017). "Thus, it is possible that an efficient supply of exogenous insulin could improve insulin signaling in the skeletal muscle, promote protein synthesis, and protect against the loss of muscle mass among patients with diabetes, especially those with a long duration of diabetes." (PMID 28246927, 2017). "These authors speculate that reduced expression of ZIP6 and ZIP7 may disrupt zinc homeostasis and thus produce defects in insulin secretion and beta cell viability that could potentially lead to the development of diabetes." (PMID 29157234, 2017). "Variants in ANRIL that disrupt its expression or function may affect compensatory increases in pancreatic β-cell mass in response to increasing demands for insulin in the pre-diabetes state." (PMID 28829354, 2017). "Recently, SKPs were shown to differentiate into endodermal-like functional insulin-producing islet-like cells in vitro, suggesting that SKPs might even be a promising new tool for diabetes research." (PMID 29141956, 2017). "Liver fat content was assessed at baseline and after insulin treatment in these diabetes cohorts." (PMID 28587667, 2017). "However, our study showed significant gaps between insulin delivery recommendations and current insulin injection practice in Nepalese patients with diabetes." (PMID 29333459, 2017). "Oldfield and colleagues investigating the long term prognosis of GDM in a multiethnic population observed that insulin treatment during pregnancy was associated with future diabetes in Caucasian but not in South Asian women." (PMID 28644881, 2017). "RES may have effects on prevention of reduction of skeletal muscle and insulin sensitivity, two important components in aging and diabetes." (PMID 28611316, 2017).
diabetes (continued). "Conversely, type 2 diabetes is characterized by insulin resistance with relative insulin deficiency (i.e., patients secrete insulin but not enough to overcome the insulin resistance) and accounts for 90–95% of diagnosed diabetes cases." (PMID 28164134, 2017). "The data of this current study indicated that newly diagnosed T2D patients with YOD had a significant increase in metformin sensitivity, which manifested itself when lowering insulin doses to maintain glycemic control compared to those with a later age of onset of diabetes." (PMID 29180640, 2017). "Functionally, diabetic cardiomyopathy is characterized by increased myocardial fibrosis, higher LV mass and wall thickness leading to both systolic and diastolic dysfunction; the latter is present even before the clinical onset of diabetes, reflecting mainly an increased insulin resistance." (PMID 28806975, 2017). "Some of the diabetes patients on insulin expressed concerns about what might happen to them with the recurring fainting they experience, especially if they have no one there to help." (PMID 28542578, 2017). "Many women diagnosed with GDM will already be undertaking insulin therapy to manage their diabetes, and thus would not only act as confounders to our data, but it would be difficult to assess the role of resveratrol as a preventative for the development of GDM." (PMID 28278187, 2017). "With respect to treatment of diabetes, 18 (12.9%) patients were on diet and lifestyle modification, 56 (40%) patients were on oral hypoglycaemic medication only and 66 (47.1%) were treated with both oral hypoglycaemics and injectable insulin." (PMID 29445546, 2017). "Lastly, the result of this study should be interpreted with caution, in that, although there was a relationship between Lp(a) and diabetes development, the predictive effects of insulin resistance and insulin secretion were much larger than the effect of Lp(a)." (PMID 28510610, 2017). "Duration of diabetes before initiation of insulin was longer in the first cohort (2.93 ± 2.74 years) compared to both newly found cases with positive antibodies (1.57 ± 1.81 years) and subjects enrolled in LADA group (1.82 ± 1.51 years), but these differences were not significant." (PMID 28573146, 2017). "In conjunction with a modest reduction in insulin secretory reserve, reflecting a below-average complement of slightly underperforming beta cells, this configuration of metabolic characteristics suffices to drive that person towards diabetes." (PMID 28175964, 2017). "Taken together, these data indicate that TMG-123 exerts glucose-lowering effects in both insulin-deficient and -resistant diabetes, and sustains reduced Hemoglobin A1c levels without affecting hepatic and plasma triglycerides even after chronic treatment." (PMID 28207836, 2017). "This nocturnal shift of caloric intake combined with the recent finding that melatonin can suppress post-prandial insulin release, raises the hypothesis that the nocturnal food intake might contribute to rising diabetes trend in both countries." (PMID 28264001, 2017). "Type 1 diabetes mellitus, namely insulin-dependent DM (IDDM), is ordinarily caused by the autoimmune damage of pancreatic islet β-cells, resulting in the pancreas unable to synthetise and secrete insulin." (PMID 29209211, 2017). "An oral glucose tolerance test (OGTT) was performed yearly and used to classify patients as normal or IGM, including impaired fasting glucose (IFG) and/or impaired glucose tolerance (IGT) and diabetes mellitus (DM), and to calculate surrogate measures of insulin secretion and/or sensitivity." (PMID 29053727, 2017). "Hyperlipidaemia is a complication of diabetes and has been reported to be due to excess mobilization of fat from the adipose tissues due to under-utilization of glucose or inhibition of the hormone sensitive lipase by insulin." (PMID 29019956, 2017). "Dramatic increase of diabetes over the globe is in tandem with the increase in insulin requirement." (PMID 28072841, 2017).
diabetes (continued). "Diabetes is a group of chronic metabolic diseases marked by high plasma glucose levels (usually fasting plasma glucose (FPG) is ≥126 mg/dL) resulting from defects in insulin secretion or insulin action or both." (PMID 28164134, 2017). "Interestingly treatment with ACEI or ARBs can improve insulin sensitivity, and a large meta-analysis found there was a 20% reduction in new onset diabetes in patients treated with ACEI or ARBs." (PMID 28419124, 2017). "We hypothesized that inflammatory markers are phase-specific for conversion from normoglycemia to pre-diabetes, diabetes and need for insulin therapy." (PMID 28258520, 2017). "Insulin was used by 80.5% of men with diabetes and 52.2% took glucose-lowering tablets." (PMID 28713837, 2017). "Type 1 diabetes mellitus is defined by the following autoimmune markers: islet cell autoantibodies, autoantibodies to insulin, autoantibodies to GAD (GAD65), autoantibodies to the tyrosine phosphatases islet antigen 2 (IA-2) and IA-2β, and autoantibodies to zinc transporter 8 (ZnT8)." (PMID 29295509, 2017). "Metformin has multiple biological effects which can contribute to anticancer effects, including either direct antiproliferative effects or through indirect mechanisms, such as lowering of circulating insulin levels and improving glycemic control in diabetes patients." (PMID 27832382, 2017). "Furthermore, aliskiren interrupted the increase of glucose and stimulated the rise of plasma insulin levels when compared to the diabetes/high fat diet group." (PMID 29046730, 2017). "Insulin therapy has been clinically used for the treatment of diabetes; however, insulin injections do not restore tight glycemic control or prevent diabetes-associated complications." (PMID 29403437, 2017). "Previous literature indicates that the physically inactive lifestyle of wheelchair users decreases their basal metabolic rate, and increases their insulin resistance as well as their glucose sensitivity, thereby precipitating the onset of diabetes mellitus together with various other co-morbidities." (PMID 28936414, 2017). "Diabetes mellitus is a group of metabolic disorders of carbohydrate metabolism characterized by high blood glucose levels (hyperglycemia), resulting from defects in insulin secretion, insulin action, or both." (PMID 28425975, 2017). "The current body of evidence supports the hypothesis that unresolved ER stress leads to ER dysfunction, reduced processing of insulin and ultimately β-cell failure and the development of overt diabetes." (PMID 28335035, 2017). "However, the clinical applications for diabetes therapy of these platforms are limited due to the weak mechanical strength, inaccurate amount of released insulin, low insulin loading, and so on." (PMID 30970930, 2017). "After STZ induction of diabetes, rats exhibited high blood glucose and low plasma insulin levels." (PMID 29109369, 2017). "A prominent example in the diabetes area is the integrated system for glucose measurement and automated insulin delivery which evolved in part due to pressure from patient-advocates and has now been developed into a FDA-approved device, heralded as the “artificial pancreas”." (PMID 29707260, 2017). "In postmenopausal women, higher endogenous oestradiol levels have been associated with higher levels of glucose and insulin, and an increase rather than decrease in diabetes risk." (PMID 28721436, 2017). "Several small studies examined association between fasting circulating insulin plasma levels and MD and found none, but have typically included healthy women without diabetes." (PMID 27832382, 2017). "Introduction of a high fat diet promotes the development of more severe diabetes characterized by hyperglycemia, decreased insulin release and sensitivity which could ultimately lead to beta cell failure." (PMID 28640904, 2017).
diabetes (continued). "However, significantly more patients suffered from diabetes mellitus (treated with insulin: 22.12 vs. 10.71%, p<0.001; treated with OAD: 64.6 vs. 26.79%, p<0.001) in the smoking and alcohol-consuming group compared to the abstinent group." (PMID 28207747, 2017). "On multivariable regression analysis adjusting for the presence of premorbid insulin-requiring diabetes and BGL change, insulin administration was independently associated with a greater percentage increase in c-peptide than no insulin administration (P = 0.04)." (PMID 28497374, 2017). "Insulin treatment of diabetes increases the likelihood of experiencing hypoglycemia." (PMID 28913365, 2017). "Many therapies for diabetes such as insulin and thiazolidinediones may improve glycaemic control, but these agents can increase the weight of patients." (PMID 27696068, 2017). "The present study identified weight-adjusted lean body mass and skeletal muscle areas as indicators of systemic insulin sensitivity and protective against weight-associated metabolic abnormalities in subjects without diabetes." (PMID 28721400, 2017). "Whether prepartum changes in thyroid hormones influence the functional maturity of beta cells at birth with consequences for glucose‐sensitive insulin secretion and the development of diabetes in later life remains to be determined." (PMID 28144955, 2017). "Moreover, Nepalese patients with diabetes have been known to perceive insulin as the “last option” available for treatment." (PMID 29333459, 2017). "Since the rescheduling of insulin, the nursing profession has sought to change the legislation to enable RN CDEs to undertake prescribing and medication supply practices to enhance their capacity and autonomy as diabetes educators." (PMID 28702089, 2017). "The importance of a combination of approaches for self-management support in individuals with type 1 diabetes is clear, including psychosocial support, education, diabetes monitoring and insulin-specific information and support, and multidisciplinary clinician support." (PMID 30291057, 2017). "Increased type 2 diabetes risk in HFE hemochromatosis is associated with one or more factors, including abnormal iron homeostasis and iron overload, decreased insulin secretion, cirrhosis, diabetes in first-degree relatives, increased body mass index, insulin resistance, and metabolic syndrome." (PMID 28331855, 2017). "The aim of the study was to investigate the nature of insulin-related prescribing errors and to evaluate the completeness of relevant information provided on the discharge summaries of insulin-treated patients with diabetes." (PMID 28852529, 2017). "Whether our present findings may be applied to other forms of diabetes, including type 1 diabetes, and if the possibility exists that cells positive for acinar markers and insulin could be differently targeted by the immune system, remain currently unknown." (PMID 28617859, 2017). "Type 1 (T1)DM results from an absolute deficiency in insulin caused by the failure of secretion by the pancreas, while type 2 (T2)DM is characterized by insulin resistance and relative insulin deficiency, either or both of which may be present at the time diabetes is diagnosed." (PMID 28926600, 2017). "MG101 was positive for a reported E224K PDX1 pathogenic variant and was diagnosed with diabetes at the age of 10 years with ketoacidosis at onset, negative for autoantibodies and has been on Insulin therapy." (PMID 28095440, 2017). "Moreover, in the present paper a positive high correlation has been indicated between the leptin concentration in the blood plasma of diabetics, both the untreated and those subject to insulin therapy, and the body mass index of the studied individuals." (PMID 28758947, 2017). "Furthermore, ROS exacerbates insulin resistance of myocytes, a key element of diabetes-induced cardiac dysfunction." (PMID 28913364, 2017).
diabetes (continued). "In this large prospective population-based cohort study, we found that serum level of DHEA was inversely associated with risk of type 2 diabetes, independent of established diabetes risk factors including BMI, fasting glucose, insulin and CRP." (PMID 27771738, 2017). "Insulin-regulated autophagy was reported recently to link diabetes and cancer." (PMID 28316059, 2017). "During diabetes, islets—cells that make insulin—can be attacked and destroyed by the immune system." (PMID 30970718, 2017). "We demonstrated that blocking insulin-specific T cell responses could reverse and even cure diabetes in mice." (PMID 29259578, 2017). "Therefore, it seemed rational to assess insulin injection practice of patients with diabetes, the objective of our study." (PMID 29333459, 2017). "In addition, the present study, for the first time to our knowledge, shows that persons with diabetes on insulin therapy have higher values of hepcidin, confirming similar results obtained from studies on rats." (PMID 28841871, 2017). "This could be a key point with a significant impact in the formation of new types of insulin-based microcrystalline preparations for treating diabetes." (PMID 28829407, 2017). "This may suggest that women with diabetes treated with insulin would develop more ER and PR-positive tumors, which we did not observe." (PMID 28076434, 2017). "Homozygous or compound heterozygous mutations in WFS1 cause WS, which is characterized by a lack of insulin secretion leading to diabetes mellitus, optic atrophy, and several other phenotypes." (PMID 29207974, 2017). "In fact, even though insulin resistance is commonly associated with obesity and aging, the ability of the pancreas to compensate by increasing insulin secretion determines whether diabetes occurs." (PMID 28951766, 2017). "We hypothesized that hepcidin levels will decrease in persons with prediabetes, while these levels will tend to correct when persons with diabetes are treated with insulin." (PMID 28841871, 2017). "Although a sizable number of studies have documented the association of inflammatory markers with type 2 DM, most of them investigated the risk to become diabetic, but not the risk of pre-diabetes and insulin therapy start." (PMID 28258520, 2017). "Aqueous or methanolic extract of L. japonicus could stimulate the proliferation of insulinoma INS-1E cells, suggesting that L. japonicus could enhance insulin secretion and could be applied as a herbal medicine to treat diabetes and related disorders." (PMID 29295591, 2017). "Natural antioxidant therapy is one of the best treatment strategies in chronic diseases such as diabetes to prevent and slow the progression of diseases and their complications such as insulin sensitivity defect, vascular health damage, inflammation, and hepatic and kidney damage." (PMID 28975102, 2017). "Our meta-analysis indicated that HOMA wasassociated with greater risk of all-cause mortality in adults without diabetes;however, the predictive role of elevated fasting insulin itself in this process wasnot statistically significant." (PMID 28811358, 2017). "Additionally, declines in insulin sensitivity had a greater effect on diabetes development than did insulin resistance, especially in Asian populations." (PMID 28430803, 2017). "Also, it is known that prolactin has direct effects on increasing insulin secretion and is closely related to diabetes." (PMID 28361687, 2017). "Diabetes mellitus refers to a group of chronic metabolic disorders characterized by hyperglycemia due to autoimmune destruction of insulin-producing beta(β)-cells (type 1 diabetes; T1D) or to extensive β-cell exhaustion and depletion often exacerbated by insulin resistance (type 2 diabetes; T2D)." (PMID 28680477, 2017). "Therefore, strategies for development of a new sources of insulin-producing cells for the treatment of diabetes have garnered significant interest." (PMID 28168007, 2017).